PLCG2 (phospholipase C gamma 2)
Description:
The production of the second messenger molecules diacylglycerol (DAG) and inositol 1,4,5-trisphosphate (IP3) is mediated by activated phosphatidylinositol-specific phospholipase C enzymes. It is a crucial enzyme in transmembrane signaling.
Synonyms: PLC-IV; PLC-gamma-2; LOC105369213; APLAID; FCAS3
Tractability: Small molecule: a structure with a bound ligand is known; it belongs to a druggable protein family. Antibody: its Gene Ontology location is reachable by antibodies, with high confidence. PROTAC: ubiquitination databases record sites on it; its protein half-life has been measured; a small molecule that binds it is known.
Target class: Enzyme; Hydrolase
Gene: Protein-coding gene on chromosome 16 (81,738,248 to 81,962,685, forward strand). Ensembl gene ENSG00000197943.
Subcellular location: Membrane raft
Subcellular location (Human Protein Atlas): Cytosol; Vesicles; Nucleoplasm
Pathways (Reactome):
Immune System: Antigen activates B Cell Receptor (BCR) leading to generation of second messengers; CLEC7A (Dectin-1) signaling; DAP12 signaling; Dectin-2 family; FCERI mediated Ca+2 mobilization; FCERI mediated MAPK activation; Generation of second messenger molecules; Role of phospholipids in phagocytosis; Signaling by CSF1 (M-CSF) in myeloid cells; Toll Like Receptor 4 (TLR4) Cascade
Disease: FCGR3A-mediated IL10 synthesis; Potential therapeutics for SARS
Hemostasis: GPVI-mediated activation cascade
Metabolism: Synthesis of IP3 and IP4 in the cytosol
Signal Transduction: Erythropoietin activates Phospholipase C gamma (PLCG)
Gene Ontology:
Molecular function: phosphatidylinositol-4,5-bisphosphate phospholipase C activity; phosphotyrosine residue binding; protein binding; protein kinase binding; protein tyrosine kinase binding; scaffold protein binding; phospholipase C activity; phosphoric diester hydrolase activity; phosphorylation-dependent protein binding
Biological process: B cell activation; B cell receptor signaling pathway; calcium-mediated signaling; cellular response to calcium ion; cellular response to lipid; intracellular signal transduction; lipopolysaccharide-mediated signaling pathway; phosphatidylinositol biosynthetic process; positive regulation of gene expression; positive regulation of neuroinflammatory response; positive regulation of NLRP3 inflammasome complex assembly; positive regulation of phagocytosis, engulfment; regulation of lipid metabolic process; release of sequestered calcium ion into cytosol; response to axon injury; antifungal innate immune response; B cell differentiation; cell activation; cellular response to lectin; Fc-epsilon receptor signaling pathway; macrophage activation involved in immune response; phosphatidylinositol metabolic process; phosphatidylinositol-mediated signaling; platelet activation; positive regulation of calcium-mediated signaling; and 27 more
Cellular component: cytoplasm; extracellular exosome; intracellular vesicle; perinuclear region of cytoplasm; plasma membrane; ruffle membrane; cytosol; membrane raft
Genetic constraint (gnomAD): Loss-of-function variants: 41 observed, 115.51 expected, observed/expected ratio (o/e) 0.35, 90% interval 0.28 to 0.46. The synonymous counts are far from expectation, so gnomAD's model fits this gene poorly and the ratio says little. Missense variants: 1,384 observed, 1,320.2 expected, observed/expected ratio (o/e) 1.05, 90% interval 1 to 1.1. Synonymous variants: 657 observed, 517.85 expected, observed/expected ratio (o/e) 1.27, 90% interval 1.19 to 1.35.
Homologues: Orthologues: chimpanzee PLCG2 (99% identical), macaque PLCG2 (98% identical), dog PLCG2 (95% identical), rat Plcg2 (95% identical), pig PLCG2 (95% identical), mouse Plcg2 (94% identical), rabbit PLCG2 (94% identical), guinea pig PLCG2 (93% identical), tropical clawed frog plcg2 (69% identical), zebrafish plcg2 (58% identical), Drosophila melanogaster sl (37% identical), Caenorhabditis elegans plc-3 (32% identical), and 3 more. Paralogues in human: PLCG1 (50% identical), PLCH1 (23% identical), PLCH2 (23% identical), PLCE1 (21% identical), PLCB3 (21% identical), PLCL2 (20% identical), PLCB1 (20% identical), PLCD4 (20% identical), PLCD1 (20% identical), PLCL1 (19% identical), PLCB2 (19% identical), PLCB4 (18% identical), and 2 more.
Diseases named in the same sentence as PLCG2 in open-access papers:
PLCG2 is named in the same sentence as 189 diseases in open-access papers, as found by Europe PMC text mining. Sharing a sentence is not in itself a finding about the gene and the disease. The quoted sentences say what the papers report.
antibody deficiency (46 papers, 2013 to 2025). "Genomic deletions in PLCG2 cause PLAID (PLCG2-related antibody deficiency and immune dysregulation), characterized by cold urticaria, immunoglobulin deficiencies, recurrent infections, atopy, and autoimmunity." (PMID 41537131, 2025). "These variants underlie two related conditions: PLCG2-associated antibody deficiency and immune dysregulation (PLAID, OMIM 614468) and its autoinflammatory counterpart APLAID (OMIM 614878)." (PMID 41464195, 2025). "Mutations in the PLCG2 gene are associated to PLCG2-associated antibody deficiency and immune dysregulation (PLAID) and to auto inflammation and PLCG2-associated antibody deficiency with immune dysregulation (APLAID) syndrome." (PMID 37033173, 2023). "Participant 1 carries the heterozygous PLCG2 gene mutation p.Ala708Pro and presented with cutaneous lesions at disease onset and mild hypogammaglobulinemia followed by recurrent infections at later stages." (PMID 36997670, 2023). "Missense mutations in PLCG2 can cause autoinflammation with phospholipase C gamma 2-associated antibody deficiency and immune dysregulation (APLAID)." (PMID 36997670, 2023). "Inherited mutations at this locus cause PLCγ2-associated antibody deficiency and immune dysregulation, in some cases with autoinflammation." (PMID 34157287, 2021). "Pathogenic mutations in PLCG2 lead to two distinct phenotypes: PLCγ2-associated antibody deficiency and immune dysregulation (PLAID) and autoinflammation, antibody deficiency, and immune dysregulation (APLAID)." (PMID 30766537, 2019). "Variants in the PLCG2 gene have been associated with autosomal dominant autoinflammation, antibody deficiency, and immunodysregulation syndrome (OMIM #614878)." (PMID 32047491, 2019). "Patients with GOF mutations in PLCG2 develop autoinflammation and PLCγ2‐associated antibody deficiency and immune dysregulation (APLAID)." (PMID 30565237, 2019). "These diseases are characterized by immune dysregulation, antibody deficiency and autoinflammation due to a complex mix of loss and gain of function of PLCγ2." (PMID 30326945, 2018). "Thereafter, the auto-inflammation and PLCγ2-associated antibody deficiency and immune dysregulation (APLAID) syndrome was described in two patients from another family." (PMID 30619256, 2018). "In contrast, distinct in-frame deletions in PLCG2 are associated with another syndrome, the PLCγ2-associated antibody deficiency and immune dysregulation syndrome (PLAID)." (PMID 28496446, 2017). "Mutations in the PLCG2 gene, which encodes an enzyme in the intracellular signaling pathway of B lymphocytes, result in a spectrum of conditions involving frequent infections, antibody deficiencies, immune dysregulation, and cutaneous manifestations." (PMID 41537131, 2025). "In contrast, PLCG2-associated antibody deficiency and immune dysregulation (PLAID) manifests with cold-induced urticarial lesions and humoral immunodeficiency, suggesting that adaptive immune signaling may also participate in cold reactivity." (PMID 41464195, 2025). "PLCγ2 signaling has broad effects across immune cells, and hypermorphic variants in PLCG2 cause autoinflammation and PLCγ2-associated antibody deficiency and immune dysregulation, thought to be at least partially due to hyperactivation of the NLRP3 inflammasome." (PMID 40842819, 2025). "Four of these patients were diagnosed with an extremely rare syndrome such as interstitial lung disease, nephrotic syndrome and epidermolysis bullosa (ILNEB) syndrome, mirage syndrome, prolidase deficiency, PLCG2-associated antibody deficiency, and immune dysregulation (PLAID) syndrome." (PMID 38231401, 2024). "In addition, gain-of-function mutations in PLCG2 have been implicated in a complex immune disorder called autoinflammation, antibody deficiency, and immune dysregulation, which are predominantly inherited and resemble PLAID." (PMID 37371495, 2023). "PLCG2 is closely associated with auto-inflammation, antibody deficiency, and immune dysregulation." (PMID 35630098, 2022).
antibody deficiency (continued). "Finally, autoimmunity has been described in patients with mutations in other genes implicated in B cell activation and proliferation, including PLCγ2, which is responsible for the PLCγ2-associated antibody deficiency and immune dysregulation (PLAID)." (PMID 34682853, 2021). "Given its prominent role in the adaptive immune system, PLCγ2 has been implicated in manifestations of immunodeficiency, including both the immunodeficiency syndrome, PLCγ2-associated antibody deficiency and immune dysregulation (PLAID) and common variable immunodeficiency (CVID)." (PMID 34157287, 2021). "Similarly, two hypermorphic Plcg2 mutations in mice (Ali5, Abnormal limb 5, D993G; Ali14, Abnormal limb 14, Y495C) lead to severe autoinflammation and antibody deficiencies." (PMID 30711010, 2019). "Furthermore, our extensive characterization of clinical manifestations, properties of immune cells, and changes in function of the encoded enzyme, PLCγ2, support a definitive diagnosis of PLCγ2-associated antibody deficiency and immune dysregulation syndrome, designated as APLAID." (PMID 32671674, 2020). "The PLCγ2-associated antibody deficiency and immune dysregulation (PLAID) results from temperature-sensitive spontaneous enzyme activity of PLCγ2 leading to mast cell degranulation." (PMID 35572516, 2022). "It is essential to distinguish APLAID from another autosomal dominant inherited disease, PLCγ2-associated antibody deficiency and immune dysregulation (PLAID), owing to deletions of the PLCG2 gene." (PMID 34093563, 2021). "Recently, 27 patients presenting with cold-induced urticaria, recurrent sinopulmonary infections, antibody deficiency, and autoimmunity, were found to have heterozygous in-frame deletions affecting the PLCG2 gene, resulting in constitutive activation of PLCγ2." (PMID 30619256, 2018). "Other studies have previously shown that deficiency in genes involved in B-cell receptor sequencing (CD19, CD21, CD81, PLCG2, PI3KCD) can lead to CVID-like antibody deficiencies." (PMID 26122175, 2015). "Missense mutations result in APLAID (autoinflammation and PLCG2-related antibody deficiency and immune dysregulation), which may present with bullous skin lesions, bronchiolitis, enterocolitis, ocular inflammation, and recurrent infections." (PMID 41537131, 2025). "One example is an association between dominantly inherited complex immune disorders and gain‐of‐function mutations in PLCγ2, such as deletions in the PLCG2‐associated antibody deficiency and immune dysregulation (PLAID) disorder that occur in the cSH2 autoinhibitory domain." (PMID 34254352, 2021). "Finally, genomic deletions within the PLCG2 coding region cause PLAID disorders, which manifest with cold-induced urticaria and variable immunologic defects, including antibody deficiency and autoimmune disease." (PMID 33823896, 2021). "This pattern is seen with NOD2 mutations in Blau syndrome and with PLCƔ2 mutations in ‘autoinflammation and phospholipase C gamma 2 associated antibody deficiency and immune dysregulation’ (APLAID) and ‘phospholipase C gamma 2 associated antibody deficiency and immune dysregulation’ (PLAID)." (PMID 34201078, 2021). "Not all PLCG2 mutations found causing BTKi resistance have yet been reported to also induce PLCγ2-associated antibody deficiency with immune dysregulation (APLAID), or without autoinflammation (PLAID), but many do." (PMID 34177947, 2021). "Phospholipase C gamma 2 (PLCG2) gene mutations might cause PLCG2-associated antibody deficiency and immune dysregulation (PLAID)/autoinflammation and PLCG2-associated antibody deficiency and immune dysregulation (APLAID) syndrome." (PMID 40170866, 2025). "Furthermore, dominantly inherited PLCG2 mutations have been documented to cause autoimmunity and inflammation (designated as PLAID for PLCγ2-associated antibody deficiency and immune dysregulation and as APLAID for autoinflammation, antibody deficiency, and immune dysregulation)." (PMID 31918402, 2020).
antibody deficiency (continued). "Though they had significantly elevated CRP and ESR, neither had antibody deficiency nor recurrent infections, which are characteristics of APLAID (PLCG2-associated antibody deficiency and immune dysregulation) syndrome." (PMID 33042144, 2020).
Alzheimer disease (29 papers, 2018 to 2026). A progressive, neurodegenerative disease characterized by loss of function and death of nerve cells in several areas of the brain leading to loss of cognitive function such as memory and language. "BACKGROUND: The PLCG2-P522R variant, which encodes a mildly hyperactive form of the PLCγ2 enzyme, has been identified as a protective genetic factor against Alzheimer’s disease (AD)." (PMID 41620758, 2026). "Phospholipase C gamma 2, proline 522 to arginine (PLCγ2-P522R) is a protective variant that reduces the risk of Alzheimer’s disease (AD)." (PMID 40038760, 2025). "PLCG2 is associated with the risk of Alzheimer’s disease (AD) through a rare missense polymorphism, rs72824905 (P522R) as well as a common variant, rs12445675, within a long non-coding RNA adjacent to PLCG2." (PMID 40585241, 2025). "One of the most differentially expressed genes in VIC9 was PLCG2, which has been implicated in osteoclastogenesis and protection against Alzheimer’s disease." (PMID 39766890, 2024). "Genome-wide association studies have identified a protective mutation in the phospholipase C gamma 2 (PLCG2) gene which confers protection against Alzheimer’s disease (AD)-associated cognitive decline." (PMID 39487477, 2024). "Microglia-mediated innate immune responses, which were led by PLCG2 mutations, promote the development of Alzheimer’s disease." (PMID 36672927, 2023). "Expression analyses in hIPSCs and knock‐in mice implicate enhanced Ca2+ release and stimulus‐dependent PIP2 depletion in macrophages and microglia in Alzheimer's disease protection associated with a rare PLCG2 coding variant." (PMID 34254352, 2021). "The gene encoding phospholipase C gamma 2 (PLCγ2) was recently linked by whole‐exome microarray genome‐wide association (rs72824905/P522R, P = 5.38 × 10−10) to Alzheimer’s disease (AD), the most common form of dementia." (PMID 34254352, 2021). "A rare coding variant (rs72824905, p.P522R) conferring protection against Alzheimer’s disease (AD) was identified in the gene encoding the enzyme phospholipase-C-γ2 (PLCG2) that is highly expressed in microglia." (PMID 32166339, 2020). "Rare, missense variants ABI3_rs616338-T and PLCG2_rs72824905-G were associated with respectively higher (OR = 1.43) and lower (OR = 0.68) risk of Alzheimer’s disease (AD) in a large study comprised of 48,402 cases and 37,022 controls." (PMID 33092647, 2020). "Missense variants ABI3_rs616338-T and PLCG2_rs72824905-G were previously associated with elevated or reduced risk of Alzheimer’s disease (AD), respectively." (PMID 33092647, 2020). "The genetic variant rs72824905-G (minor allele) in the PLCG2 gene was previously associated with a reduced Alzheimer’s disease risk (AD)." (PMID 31131421, 2019). "In 2017, a genome-wide association (GWA) study of Alzheimer’s disease (AD) showed that the rare nonsynonymous variant in the PLCG2 gene (rs72824905-G; p.Pro522Arg; NC_000016.9:g.81942028C > G) reduced AD risk (OR = 0.68, p = 5.4 × 10−10)." (PMID 31131421, 2019). "In line with this suggestion, a variant of PLCG2 (rs72824905: p.Pro522Arg) has very recently been shown to be associated with protection against the development of late-onset Alzheimer ́s disease." (PMID 30344948, 2018). "Rare nonsynonymous variants in ABI3 (p.Ser209Phe; rs616338-T) and PLCG2 (p.Pro522Arg; rs72824905-G) have recently been implicated in conferring risk and protection, respectively, for Alzheimer’s disease (AD)." (PMID 30326945, 2018). "Rare coding variants ABI3_rs616338-T and PLCG2_rs72824905-G were identified as risk or protective factors, respectively, for Alzheimer’s disease (AD)." (PMID 30326945, 2018). "A rare coding variant, P522R, in the phospholipase C gamma 2 (PLCG2) gene has been identified as protective against late-onset Alzheimer’s disease (AD), but the mechanism is unknown." (PMID 35895133, 2022).
Alzheimer disease (continued). "Here, we add six variants associated with Alzheimer’s disease risk (near APP, CHRNE, PRKD3/NDUFAF7, PLCG2 and two exonic variants in the SHARPIN gene)." (PMID 34099642, 2021). "Human genetic studies have linked rare coding variants in microglial genes, such as TREM2, and more recently PLCG2 to Alzheimer’s disease (AD) pathology." (PMID 34615897, 2021). "Recent genome-wide association studies have identified several Alzheimer’s disease (AD)-associated risk loci in genes selectively or preferentially expressed in microglia (e.g. TREM2, ABI3, PLCG2)." (PMID 32917267, 2020). "Rare coding variants in TREM2, PLCG2, and ABI3 were recently associated with the susceptibility to Alzheimer’s disease (AD) in Caucasians." (PMID 30705288, 2019). "This further supports the hypothesis that modifying PLCγ2 may be a potential therapeutic strategy to manipulate microglial functions in Alzheimer’s disease." (PMID 34615897, 2021). "PLCG2 variants have been also associated with inflammatory bowel disease (IBD) and one rare PLCG2 variant has been reported to strongly associate with the protection from the development of Alzheimer's disease (AD)." (PMID 31918402, 2020). "Moreover, research has also suggested PLCγ2 may have a role in Alzheimer’s disease (AD) and some solid cancers." (PMID 34157287, 2021). "Thus, the role of PLCγ2 in Alzheimer’s disease may be complex." (PMID 34254352, 2021). "PLCγ2 also sits downstream of CSF1R, inhibitors or which are currently in trials in the context of Alzheimer’s disease." (PMID 34254352, 2021). "Using bulk RNA-Seq (N=1249) data from the Accelerating Medicines Partnership-Alzheimer’s Disease Consortium (AMP-AD), we investigated whether PLCG2 expression increased in the brains of LOAD patients." (PMID 35180881, 2022). "In addition, a panel of Alzheimer’s-disease relevant genes, which are consistently up-regulated in the transgenic CRND8 mouse brain over time, also reveals variable (Abi3 versus Plcg2)—and sometimes unexpected (Trem2)—responses to Aβ peptides in microglia." (PMID 34127518, 2021).